CDK4 (cyclin dependent kinase 4)
Diseases named in the same sentence as CDK4 in open-access papers (continued):
Sharing a sentence is not in itself a finding about the gene and the disease.
melanoma (continued). "It has been reported that innate resistance to anti-PD-1 immunotherapy is related to the genetic aberrations in the CDK4 pathway, including CDK4, CCND1 gain, and CDKN2A loss in patients with advanced melanoma." (PMID 39593745, 2024). "The melanoma cell line WM3211, derived from the primary lesion (VGP) and wild type for BRAF, PTEN, N-RAS, and CDK4 and with a mutation at position 576 in the c-KIT gene, showed the lowest tendency to activate caspase-3." (PMID 39596342, 2024). "This cell line was derived from a carcinogen-induced primary melanoma that developed in the skin of an Hgf-Cdk4 mouse." (PMID 38360887, 2024). "A dual LoF/GoF screen carried out in NRAS-mutated Meljuso melanoma cells treated with a combination of MEK1/2 and CDK4/6 inhibitors uncovered that activated KRAS was sufficient to confer resistance." (PMID 38255778, 2024). "Here, we report that Gnaq/11 hotspot mutations occur as early oncogenic drivers during the evolution of primary melanomas in Hgf-Cdk4 mice." (PMID 38360887, 2024). "In turn, the PIK3CA E545K mutation pre-existing in NRAS-driven melanoma was indicated as an aberration that caused resistance to MEK and CDK4/6 inhibitors in melanoma patients." (PMID 39340537, 2024). "Melanoma cell proliferation is strongly dependent on the CDK4/6-mediated inhibition of cellular senescence." (PMID 39791714, 2024). "In subgroup III, CDK4 amplification and PRKDC amplification jointly promoted increased CDK4 protein expression and kinase activity in melanoma patients, accelerating the proliferation rate of melanoma and leading to poor prognosis." (PMID 39039072, 2024). "The NRAS mutated subtype, which accounts for a quarter of all melanoma cases, lacks such a targeted approach but ongoing clinical trials are assessing the effects of combined MEK and CDK4/6 inhibitors (NCT01781572; NCT02065063)." (PMID 37420093, 2023). "Immunoblots showed a concentration-dependent decrease of cyclin D1 and CDK4 expression level in melanoma cells treated for 24 h with HPF." (PMID 36674794, 2023). "Germline pathogenic variants (GPVs) in melanoma susceptibility genes CDKN2A, CDK4, and BAP1 are identified in up to 40%, 0.7%, and 1.0% of familial melanoma cases, respectively." (PMID 36876055, 2023). "Although CDKN2A was first identified in 1994, followed by cyclin-dependent kinase 4 (CDK4) in 1996, most familial melanoma genes were only discovered after 2010 when next-generation sequencing technologies were introduced." (PMID 36901857, 2023). "Along with CDK4, they correspond to less than 3% of melanoma-prone families in the studied populations around the world; nevertheless, the majority of cases remain without known genetic etiology." (PMID 37958811, 2023). "In animal models of melanoma, the mixture of CDK4/6 inhibitors and anti-PD-1 antibodies substantially inhibited cancer growth." (PMID 36768557, 2023). "Taken together, our data describe how NRAS mutant melanoma adapt to CDK4/6 and MEK inhibition by triggering an EMT programme." (PMID 37420093, 2023). "Here we characterised the response of three different NRAS mutant melanoma cell lines to a combination of CDK4/6 and MEK inhibitors over 33 days." (PMID 37420093, 2023). "One phase 2 clinical trial highlighted the potential of CDK4 inhibitor ribociclib in combination with the MEK inhibitor binimetinib as a treatment approach in melanoma, particularly in cases with specific genetic alterations involving CDK4." (PMID 37504268, 2023). "Recently, it was observed that CDK4/6 activity and PD-L1 expression are correlated in melanoma patients." (PMID 36768557, 2023). "Biologically, the activation of FOXM1 by CDK4/6 is critical for CDK4/6-mediated cell cycle entry, suppressing the levels of reactive oxygen species (ROS), and protecting cancer cells (breast, melanoma, sarcoma) from senescence." (PMID 37686402, 2023).
melanoma (continued). "Senescent melanoma cells generated by CDK4/6 inhibitors have been shown to generate CCL5 via activation of NF-kB, a member of the released factors." (PMID 36768557, 2023). "CDKN2A, CDK4, and BRCA1-associated protein 1 (BAP1) have been identified as high-risk melanoma susceptibility genes." (PMID 37504268, 2023). "In melanoma, CDK4 is often overexpressed, which can contribute to the uncontrolled proliferation of melanoma cells." (PMID 37504268, 2023). "Along with overexpression, CDK4/6 upregulation is a common occurrence in various malignancies (melanoma, leukemia, lymphoma, glioma, sarcoma, etc.)with distinct tissue selectivity for CDK4/6." (PMID 36768557, 2023). "Hyperactivation of the cyclin-dependent kinase 4/6 (CDK4/6)-pRb-p16INK4A pathway has been reported in approximately 90% of melanomas." (PMID 35525274, 2022). "The Ras–Raf–MAPK/PI3K–AKT signaling pathway, as a common signaling pathway in melanoma, promotes tumor proliferation and survival by regulating CDK4 and cyclinD1." (PMID 35893303, 2022). "For example, acral and mucosal melanomas have fewer BRAF mutations but more frequent KIT mutations, amplifications of CCND1, CDK4, and MDM2, and deletion of SPRED1." (PMID 35706047, 2022). "Downregulation of the E2F family of transcription factors except E2F6 was reported in studied malignant melanoma cell lines along with a time-dependent decrease in cyclin A, cyclin D3, cyclin E, cdk2, cdk4, and cdc2 expressions." (PMID 36362950, 2022). "CDK4 Amplification was seen in several tumors, such as head and neck mucosal melanoma, urinary bladder cancer, liposarcomas, melanoma and lung cancer." (PMID 36531058, 2022). "FAK-I also reduced CDK4 protein expression and cell proliferation in multiple human melanoma cell lines, showing this effect was not specific to murine melanoma." (PMID 35525274, 2022). "Previously, we have established and conducted a population-based PDX trial consisting of 24 models established from 24 melanoma patients, which demonstrated robust antitumor effect of palbociclib in CDK4-amplified melanoma." (PMID 35546399, 2022). "CDK4 appears in 90% of melanoma cases; furthermore, MAPK signaling pathway upregulates D1 cycling expression, resulting in CDK4 pathway enhancement." (PMID 36014478, 2022). "Melanoma SK‐MEL‐103 cells treated with the CDK4/6 inhibitor, palbociclib, displayed SAβGal staining and increased protein levels of the lysosomal membrane proteins LAMP1 and LAMP2." (PMID 36087066, 2022). "We chose B16F10 melanoma as they have a large deletion within the CDKN2A locus (encoding p16INK4A) and increased CDK4/6 activity." (PMID 35525274, 2022). "In fact, by targeting genes such as Cyclin C, Cyclin D1, and CDK4, miR-206 functions as a cell-cycle regulator and tumor suppressor in multiple melanoma cell lines." (PMID 35804995, 2022). "Circos plots further showed that hsa-miR-122-5p, which was profoundly upregulated in our metastatic UM samples, is implicated in stemness of cells and melanoma development by targeting Nodal growth differentiation factor (NODAL), SOX11, WNT11 and CDK4." (PMID 36619870, 2022). "Genetic predisposition accounts for nearly 10% of all melanoma cases and has been associated with a dozen moderate- to high-penetrance genes, including CDKN2A, CDK4, POT1 and BAP1." (PMID 35085295, 2022). "For example, combination of CDK4/6 inhibitor with MEK inhibitor leads to apoptosis in melanoma cell lines." (PMID 35327487, 2022).
melanoma (continued). "We and others have recently shed new light on the immunomodulatory effects of CDK4/6i, both alone and in combination with current melanoma standard-of-care therapies, including ICI (targeting PD-1, PD-L1, and CTLA-4) and targeted BRAF and MEK therapies." (PMID 35444175, 2022). "Overall, we provided potential melanoma therapeutic regimens by treatment with ABZ alone or in combination with CDK4/6 inhibitors." (PMID 35383224, 2022). "Overall, our data demonstrate the potential for FAK-Is to reduce melanoma growth through forced nuclear localization of FAK to regulate CDK4/6 expression." (PMID 35525274, 2022). "Treatment with MG-132 was able to rescue CDK4/6 protein expression in both murine and human melanoma cells." (PMID 35525274, 2022). "PHA-793887 is an inhibitor of multiple cyclin-dependent kinases (CDKs), with activity against CDK2, CDK1, and CDK4, and has been validated to enhance immunotherapy against melanoma." (PMID 35680563, 2022). "Recent revelations into the immunotherapeutic activity of CDK4/6i, therefore, have significant implications for the utility of these agents as melanoma therapies." (PMID 35444175, 2022). "Here, we show for the first time an AKT1 isoform-specific role in cellular senescence induced by CDK4/6 inhibition in human melanoma cell lines." (PMID 35158840, 2022). "The WB assay result showed that overexpression of RAI14 in knockdown melanoma cell lines partially restored the expression of CDK4 and CCND1." (PMID 36233342, 2022). "Taken together, we revealed a previously unappreciated function of ABZ in antimelanoma proliferation by inducing cell cycle arrest and apoptosis and provided a novel combined therapeutic regimen of ABZ plus CDK4/6 inhibitor treatment in melanoma." (PMID 35383224, 2022). "For example, dual inhibition of CDK4 and CDK6 has little clinical impact on colorectal cancer and melanoma, as other CDKs such as CDK1–3 compensate for the loss of CDK4 and CDK6." (PMID 35884441, 2022). "Such discoveries have highlighted the immunotherapeutic potential of CDK4/6i, which has significant implications for the utility of these agents for treating melanoma." (PMID 35444175, 2022). "BRAF class 1 mutations occurred predominately in sole (25.4% vs. 2.7%) compared to subungual melanoma, in contrast with CDK4 amplification (5.6% vs. 24.3%)." (PMID 35706047, 2022). "In the present study, we demonstrated that FAK inhibition increased FAK nuclear localization in B16F10 melanoma cells, leading to decreased stability of CDK4/6 protein and cell cycle arrest." (PMID 35525274, 2022). "Herein we review the available literature to depict a comprehensive landscape about CDK4/6 inhibitors in melanoma." (PMID 34071228, 2021). "Pathogenic variants in many other genes (including c-kit, MAGE-1, CDK4, BAP1, and BRCA2) have also been associated with melanoma." (PMID 33509032, 2021). "Regarding immunotherapy, clinical trial that evaluating combinations of CDK4/6 inhibitors and immunotherapy in advanced solid tumors, including melanomas, are ongoing." (PMID 34071228, 2021). "Given that fatty acid oxidation also drives mitochondrial metabolism by feeding into the TCA cycle, the role of this pathway in metabolic reprogramming following CDK4/6 inhibition in melanoma cells was investigated." (PMID 33572972, 2021). "Similar upregulation of MHC Class I by CDK4/6i was also demonstrated in the murine melanoma cell line B16-OVA with co-culture experiments showing enhanced IFN-γ and TNF-α release when treated with OT-1 T cells." (PMID 34944961, 2021). "We selected a CDK4/6 inhibitor, palbociclib, that is currently approved in clinical practice and most advanced in clinical trials and we treated four melanoma cell lines." (PMID 34485433, 2021).
melanoma (continued). "Our findings are in accordance with synergistic antitumoral effects of the MEKi and CDK4/6i in various other tumor cell models, including neuroblastoma, neuroendocrine prostate carcinoma, melanoma, colorectal cancer, pancreatic cancer, and NSCLC models." (PMID 33807122, 2021). "Based on the importance of metabolism in targeted therapy response in melanoma, we characterise how CDK4/6 inhibition reprograms metabolism in BRAFV600 melanoma, alone and in combination with BRAF and MEK inhibitors." (PMID 33572972, 2021). "A recent study leveraging single-cell RNA-seq in tumors from melanoma patients treated with anti-PD-1 identified the CDK4/6 axis as a tumor-intrinsic resistance mechanism." (PMID 34172722, 2021). "Our results show that their potential role in the CCDN1/CDK4 complex as an essential oncogenic driver in various cancer types, including melanoma." (PMID 33562431, 2021). "Overexpression of MDM2 and CDK4 occurs in several tumour types such as liposarcoma, melanoma and osteosarcomas, and targeting both MDM2 and CDK4 is of interest in such settings, evidenced by a synergistic effect in liposarcomas." (PMID 34911439, 2021). "Approximately 90% of melanoma exhibit some cell cycle pathway dysregulation which provides a strong rationale to combine CDK4/6i with BRAF-MEKi." (PMID 34944961, 2021). "In summary, our metabolic analyses have revealed that inhibition of CDK4/6 upregulates mitochondrial function in BRAF mutant melanoma cells." (PMID 33572972, 2021). "In order to assess a role for glutamine metabolism in metabolic reprogramming following CDK4/6 inhibition in melanoma, we first assessed the levels and activity of a key enzyme involved in glutamine metabolism, glutaminase (GLS1)." (PMID 33572972, 2021). "In contrast to these reports, which highlight a positive role of mTOR in senescence induced by CDK4/6 inhibition, a significant inhibition of mTORC1 signaling was observed in melanoma and glioma cells after treatment with the CDK4/6 inhibitor palbociclib." (PMID 34360912, 2021). "Loss of CDKN2A was also commonly found in BRAFi resistant melanomas and is linked to the MAPK pathway as an inhibitor of the downstream effectors cyclin D and cyclin-dependent kinase 4 (CDK4)." (PMID 34066966, 2021). "Collectively, although CDK4/6 inhibition has no substantial effect on the metabolic phenotype following BRAF/MEK targeted therapy in melanoma, CDK4/6 inhibition alone significantly enhances mitochondrial metabolism." (PMID 33572972, 2021). "Less common melanoma susceptibly genes include CDKN2A/ARF, CDK4 (cyclin-dependent kinase 4), TERT, MITF (melanocyte inducing transcription factor), BAP1 (BRCA1 associated protein-1), and POT1 (protection of telomeres 1)." (PMID 34440462, 2021). "Together, these data suggest that neither MYC nor the mTOR pathway is a key driver of enhanced mitochondrial metabolism following CDK4/6 inhibition in melanoma cells." (PMID 33572972, 2021). "Considering the current clinical availability of CDK4/6 inhibitors, increasing interest has emerged in CDK4/6 inhibition in melanoma." (PMID 34071228, 2021). "It was recently shown that palbociclib (CDK4/6 inhibitor), in addition to increasing the MHC class I expression, can alter the peptide-MHC repertoire in melanoma cell lines to reflect the intracellular response to CDK4/6 inhibition." (PMID 33807608, 2021). "The addition of cyclin-dependent kinase 4/6 inhibitors to combination BRAF-MEK inhibitors can also greatly improve the duration of response against melanoma." (PMID 34944961, 2021). "Co-administration of MDM2 inhibitor was beneficial in melanoma cells resistant to CDK4/6 inhibition, characterised by abnormal PI3K/AKT (phosphoinositide 3-kinase/protein kinase B) signalling, and CDK4/6 inhibition upregulated cyclin D1 that sequestered p21." (PMID 34911439, 2021).
melanoma (continued). "Forced up-regulation of let-7b in melanoma cells has led to significant decrease in the expression of cyclins D1, D3, and A, and CDK4." (PMID 33968718, 2021). "For example, CDK4/6 inhibitors modulate immune functions, such as antigen presentation, and induce T cell memory in clinical and experimental melanomas." (PMID 34359625, 2021). "We first looked at an extended list of high-risk genes predisposing to melanoma (ACD, CDKN2A, CDK4, POT1, TERF2IP, and TERT) or RCC (CDKN2B, FH, FLCN, MET, PBRM1, PTEN, SDHs, TSCs, and VHL) or both (BAP1 and MITF)." (PMID 34067022, 2021). "miR-198, regulated by hsa_circ_0025039, inhibited cell growth, glucose metabolism, and invasion in malignant melanoma via targeting CDK4." (PMID 33897771, 2021). "Cyclin D1, CDK6, and CDK4 are significantly downregulated in human melanoma cells after ASNS depletion while p21, a CDK inhibitor, is obviously upregulated in response to ASNS knockdown." (PMID 34540668, 2021). "This supports the combination of CDK4/6 inhibitors with MEKi for better synergy, which has been investigated in other cancers, such as melanoma, colorectal and NSCLC56." (PMID 34907286, 2021). "Copy number variants, including loss of CDKN2A and gain of KIT, CDK4 and MYC, were frequently seen in mucosal melanomas." (PMID 34571863, 2021). "The results revealed a similar trend of the negative association of various immune cell infiltrations with CDK2, CDK4, and STAT3 SCNA in GBM and CDK2/4/6/STAT3 SCNA in melanoma." (PMID 33668805, 2021). "In CMM10 melanoma cells, the differences between CDK4/6 inhibitor treated cells and control cells were less obvious, although with palbociclib concentrations ≥2.5 μM cell numbers slowly but steadily decreased with increasing concentrations of the compound." (PMID 34485433, 2021). "The CCND1 and CDK4 genes are found to be altered in a minority of melanomas, representing less than 5%, and depend on the melanoma type." (PMID 34571969, 2021). "Our findings are in accordance with the synergistic antitumoral effects of MEKi and CDK4/6i shown in various other tumor cell models, including neuroblastoma, neuroendocrine prostate carcinoma, melanoma, colorectal cancer, pancreatic cancer and NSCLC models." (PMID 33807122, 2021). "In detail, upon treatment with CDK4/6 inhibitors, melanoma cells increase the levels of cyclin D1, which is a master regulator of cell cycle progression." (PMID 34071228, 2021). "Other genes including CDKN2A, CDK4, BAP1, POT1, ACD, TERF2IP, and TERT are known for their high penetrance as predisposing mutations for melanoma." (PMID 33339193, 2020). "Numerous genes have been associated with melanoma: beyond CDKN2A and CDK4, primarily included as high-risk genes for familial melanoma, BAP1, POT1, and MITF were recently also identified as potential high-risk melanoma susceptibility genes." (PMID 33322357, 2020).